CD4 (CD4 molecule)
Diseases named in the same sentence as CD4 in open-access papers (continued):
Sharing a sentence is not in itself a finding about the gene and the disease.
melanoma (continued). "Melanoma patients were arbitrarily stratified into two groups according to clinical response to nivolumab therapy, as indicated in the Material and Methods paragraphs, to assess the correlation between CD4+CD26high T lymphocytes and clinical benefit to nivolumab." (PMID 37170241, 2023). "Lastly, to address whether the immune-inflammatory perturbations we observed in melanoma patients at baseline are influenced by currently available nivolumab treatment, we measured the frequency distribution of circulating CD4+CD26high levels in a sub-cohort of 33 cases." (PMID 37170241, 2023). "Considering the effect of CD4+ CTLs in suppressing other cancers, including melanoma, breast cancer, bladder cancer, and colorectal cancer via their cytotoxicity, whether the dual role of CD4+ CTLs we found in this study is specific to OSCC needs to be verified in the future." (PMID 38077321, 2023). "In order to observe whether AsC can change the tumor immune microenvironment during the inhibition of lung cancer and melanoma, we examined the proportions of various immune cells in mouse tumor tissue cells, including CD4+ T cells, CD8+ T cells and Natural Killer (NK) cells." (PMID 38132921, 2023). "Thus, appropriately primed CD4 T cells may be useful for both stand-alone therapies as shown in a melanoma clinical trial and as multi-faceted tumor immunotherapy." (PMID 35903540, 2022). "Intratumoral injection of RdB/IL12/shVEGF generates massive infiltration of differentiated CD8+ and CD4+ T cells, DCs and NK cells to tissues surrounding the necrotic region of the tumor, inducing a strong antitumor effect in an immune-competent B16-F10 melanoma model." (PMID 36428682, 2022). "In melanoma models with T cell dysfunction, PSGL-1 deficiency leads to programmed cell death-1 (PD-1) downregulation, an improved T cell response, and tumor control, and PSGL-1 acts as a negative regulator of CD4+ T cells in a variety of diseases, including cancer." (PMID 35710862, 2022). "We are aware of one study that studied the risk of melanoma among individuals infected with HIV by considering only recent CD4 counts that reported elevated relative risks for individuals with CD4 counts under 200 and 201–499 cells/μL, but not for those with CD4 counts greater than 500 cells/μL." (PMID 34256861, 2021). "Besides, an impressive result was found, as well as in their melanoma trial, that robust CD4+ T-cell response against immunized neoantigens that was even higher than CD8+ T-cell response was detected, despite the use of MHC class I binding prediction algorithms." (PMID 33503926, 2021). "Thus, CCR10 and CXCL12/CXCR4 may regulate homing of CD4+ Tregs to B16 melanoma tumors while invasion of NBL tumors by CD4+ Tregs is likely governed by CCL28/CCR10 and CXCL12." (PMID 34721405, 2021). "Neoantigens can induce both CD4 and CD8 T-cell responses, and reactivity of one or both T-cell subsets against mutated tumor peptides was confirmed initially by testing tumor-infiltrating T-cell (TIL) products expanded from melanoma, epithelial cancer, cervical cancer and colorectal cancer biopsies." (PMID 34201655, 2021). "Most CD4+ T cells could not recognize cancer cells directly due to a lack of MHCII (Major Histocompatibility complex II) in most solid cancer cells (except melanoma and breast cancer), whereas CD4+ and CD8+ T cells are activated in spleens under immune activation and inflammatory conditions." (PMID 33668827, 2021). "Of the immune cells investigated, M1 macrophages, activated memory CD4+ T cells, T follicular helper (Tfh) cells and CD8+ T cells correlated with response and prolonged PFS and OS, while resting memory CD4+ T cells was associated with unfavorable prognosis in melanoma and urothelial cancer." (PMID 34220837, 2021).
melanoma (continued). "Additionally, in a similar TRP-1 TCR transgenic adoptive transfer model with B16 melanoma in RAG1-deficient lymphopenic hosts, the addition of OX40 agonists and the chemo-therapy cyclophosphamide enhanced tumor killing by cytotoxic CD4+ T cells, in a manner dependent on EOMES expression." (PMID 34910940, 2021). "The similar variation of DNT cells and CD4, as well as other immune actors, may improve the reliability of lymphocyte assessment and warrants further investigation of DNTs as a potential target in checkpoint inhibitor resistant melanoma." (PMID 33669266, 2021). "A recent study showed that an increase in anti-melanoma immunity, induced by the treatment with diosgenin, a natural steroidal saponin, was characterized by a change in the microbiota, with a reduction of Bacteroidetes, and augmented intra-tumor CD4, CD8 and IFN-γ expression." (PMID 34359902, 2021). "Cox analysis implied that higher levels of CD4+ T cell (HR = 20.246, P = 0.049), macrophage (HR = 12.960, P = 0.033), BIRC5 expression (HR = 1.321, P = 0.001) and lower levels of neutrophil (HR < 0.001, P = 0.020) were risk factors for prognosis in melanoma patients." (PMID 33072607, 2020). "Finally, the surface markers CD69 and PD-1 were also found to be expressed on CD4+ T cells in metastatic tumors but the prognostic value of assessing these markers using immunohistochemistry or in situ IF remains to be demonstrated in melanoma." (PMID 33013886, 2020). "While baseline density does not appear to correlate with clinical activity of ipilimumab, pre-existing CD8+ (but not CD4+) T cell infiltration at the invasive tumor margin and within the tumor core is associated with response to anti-PD-1 therapy in patients with melanoma." (PMID 33268350, 2020). "In another study, melanoma (B16F10) or breast cancer (E0771) cells injected in CXCR3−/− mice showed a significant increase in tumor growth compared to wild type (WT) mice, which was associated with a lower prevalence of CD8+ and CD4+ T cells as well as NK cells." (PMID 31216755, 2019). "Furthermore, MHC II vaccines made from murine sarcoma, mammary carcinoma and melanoma cells activated tumor-specific CD4+ T cells and mediated rejection of established primary and metastatic mouse tumors, validating the MHC II vaccine concept in vivo in animal models." (PMID 30956760, 2019). "Moreover, PCI-based vaccination caused tumor regression independent of MHC class II or CD4 T cells presence in melanoma bearing mice." (PMID 31333674, 2019). "In the case of immune checkpoint blockade therapy, it was recently shown that an increase in a subset of central “memory-like” (CD27+Fas−CD45RA−CCR7+) CD4+ T cells in patients with malignant melanoma could be used as a predictor of clinical response to PD-1 blockade therapy." (PMID 31379821, 2019). "Thus, our findings collectively revealed that curcumin and apigenin not only regulated the sensitivity of tumor to immune killing through the suppression of PD-L1 expression on melanoma cells, but also increased the abundance of CD4+ and CD8+ T cells in the tumor xenograft-bearing mouse hosts." (PMID 30373602, 2018). "Hence we asked whether the combination of 17-AAG, responsible for induction of Tyrp1, and adoptive transfer of cytotoxic CD4+ T cells specific for Tyrp1 can enhance the anti-tumor immune response by delaying recurrence of B16 melanomas." (PMID 29481571, 2018). "Interestingly, this premature contraction of the CD4+ TNaive cell pool in young melanoma patients could be entirely attributed to a decrease of CD31+ thymic emigrant CD4+ TNaive cells." (PMID 29546435, 2018). "TH9 cells, which have been characterized in 2008 as a proinflammatory CD4 T cell subset that promotes protection against parasites and drives tissue inflammation in colitis, actually harbor potent IL-9-dependent anti-cancer properties in solid tumors and especially melanoma." (PMID 27832300, 2017).
melanoma (continued). "Importantly, these peptide-specific CD4+ T cells could strongly recognize CSPG4 expressing melanoma cells, suggesting that the identified peptides are naturally processed by tumor cells." (PMID 28668095, 2017). "However, in view of the fact that CD4+ T cells play a crucial role in optimal tumor-specific CTL activity and are themselves capable of recognizing and controlling melanoma, it seems unwise to prevent potential CD4+CD25hiFoxP3+ T cell accumulation at the cost of tumor-specific CD4+ T cells." (PMID 28401257, 2017). "We next posited that lymphodepletion with 5Gy TBI or chemotherapeutics, which can have toxic side effects in patients, could be bypassed in animals with established melanoma if they were transiently depleted of host CD4+ T cells, given a tripartite ACT therapy and then treated with LPS." (PMID 26885368, 2016). "To examine how collaboration between tumor-specific CD4+ T cells and B cells, and the production of isotype switched antibodies to tumor antigens affect tumor growth, we made use of antigen receptor transgenic B cells and CD4+ T cells specific for a neo-antigen expressed by the B16 mouse melanoma." (PMID 27121060, 2016). "Furthermore, we showed that B220+ cell depletion but not asialo-GM1+ cell depletion was similar to the depletion of NK1.1+ cells, suggesting that B220+NK1.1+ pre-mNK cells were playing a role in dampening the CD4+ anti-tumor response in our preclinical model of melanoma." (PMID 26981246, 2016). "Inhibition of CD4+ T cell proliferation in the presence of melanoma cell lines resulted significantly lower in naïve cells (% of inhibition ± SD: 5.82 ± 5.04) than in effector memory (37.42 ± 14.86, p = 0.0048) and central memory (25.17 ± 5.7, p = 0.0079) CD4+ T cells." (PMID 26329660, 2015). "However, therapeutic anti-tumor effects of MHC-II-restricted tumor-recognizing T cells have not been tested in clinical trials except for a single report that demonstrated that adoptive transfer of NY-ESO-1-specific CD4+ T cell clone in a melanoma patient led to complete remission." (PMID 26447332, 2015). "It remains unclear why higher frequencies of EphA2- and MAGE-6-specific CD4+ T cells were identified in female patients, although it has been previously reported that female melanoma patients have a generally better prognosis (i.e., longer survival) when compared to their male counterparts." (PMID 25325015, 2014). "Furthermore, a preoperative local administration of the TLR9 agonist CpG B-type oligodeoxynucleotide (ODN) PF-3512676 (formerly known as CPG 7909) lowers the frequency of CD4+CD25high Treg cells in the sentinel lymph node of 23 patients with Stage I to III melanoma." (PMID 23378947, 2013). "In this study, we sought to investigate whether functional inactivation of CD4+CD25+FoxP3+ Treg with anti-CD25 monoclonal antibody (mAb) PC61 prior to DC/tumor vaccination would significantly improve immunotherapy in the murine B16 melanoma model." (PMID 23768240, 2013). "Indeed, the efficacy of this strategy has been hinted by some elegant clinical studies, which showed that better immunological and clinical responses were obtained in melanoma or myeloma patients that had received CD4+ T cell-containing donor cells following preconditioning chemotherapy." (PMID 22400040, 2012). "However, the significance of this property has been largely ignored, until recently two studies have provided compelling evidence that cytotoxic CD4+ T cells developed in a lymphopenic environment can eradicate established melanoma as a result of direct killing of the tumor cells through granzyme B." (PMID 22400040, 2012). "However, in two melanoma patients we could detect a CD4+ specific release of TNF-α and to a lesser extend IFN-γ in response to IDOlong." (PMID 22539948, 2012).
melanoma (continued). "Therefore, in the current study we investigated the effects of ipilimumab on the gene expression profile of CD4+ and CD8+ T cells by microarray analysis when it was administered as adjuvant therapy to 12 patients in a trial for patients with high risk resected melanoma." (PMID 22788688, 2012). "Interestingly, high-avidity CD4 T cells are also capable of mediating vitiligo, which may relate to the fact that both melanocytes and melanoma cells can express MHC II molecules." (PMID 21911918, 2011). "Therefore significant clinical evidence supports the theory that melanoma-associated vitiligo is a CD8 T cell mediated phenomenon, although antibodies and/or CD4 T cells may also play roles." (PMID 21911918, 2011). "Additionally, Th17 cells amplified adoptive CTL immunotherapy in one mouse model, and we have identified one CD4+ Th17 clone from an NPC patient that could inhibit melanoma growth in a NOD/SCID mouse model (unpublished data)." (PMID 22051182, 2011). "Therefore, as judged by their TCR Vβ usage, and in accordance with earlier studies on DP T cells present in lesional skin of patients with systemic sclerosis, melanoma infiltrating DP T cells would have a clonal origin distinct from that of SP CD4+ and CD8+ SP cells." (PMID 20052413, 2010). "In addition, the TRP-1284–298-specific CD4+ T cell line was used to investigate if human melanoma cell lines could serve as stimulatory targets." (PMID 21152437, 2010). "To investigate how populations of CD4+ effector and Treg cells change during immune response in cancer and how these two T cell subsets contribute to the T cell population in the tumor-draining lymph nodes and tumor tissue, we have followed immune response to transplantable B16 melanoma." (PMID 21049016, 2010). "The association of immunity with enhanced class II and costimulatory molecule expression and in vitro activation of antigen-specific CD4+ T cells by TSA-treated melanoma cells is consistent with the hypothesis of direct antigen presentation by tumor cells in vivo." (PMID 18070359, 2007). "In preclinical models and in patients with BRAF‐mutant melanoma, treatment with BRAF inhibitors (BRAFi) increased intratumoral CD4+ and CD8+ lymphocytes." (PMID 41514118, 2026). "Building on promising work in melanoma, subsequent studies in the 1990s characterized cSCC as a T-cell-rich tumor, dominated by CD3+ and CD4+ lymphocytes, but provided little insight into their function." (PMID 41562715, 2026). "This combination significantly increased CD4+ and CD8+ T-cell infiltration into tumors, leading to reduced tumor growth and prolonged survival in melanoma-bearing mice." (PMID 40867277, 2025). "In a B16F10 melanoma model, auranofin treatment increased lung tumor coverage, IL-10 serum levels, and FOXP3+CD44+CD4+ T cell frequencies." (PMID 41300507, 2025). "In this study, we described a positive correlation between melanoma ICAM-1high expression and infiltration of antitumorigenic M1 macrophages and CD4+ and CD8+ T cells." (PMID 39867570, 2025). "In this regard, it is worth noting that previous work with a B16 mouse melanoma cell line expressing CXCR4, CCR5, and WT CD4 demonstrated that it was resistant to HIV-1 Env-mediated fusion because of the reduced CD4 lateral mobility in these cells." (PMID 40284914, 2025). "In B16-F10 melanoma models, c-di-GMP-PNT significantly upregulated IFN-β, TNF-α, IL-6, and IL-1β expression, activated CD4+/CD8+ T cells, and enhanced tumor cell killing." (PMID 40933890, 2025). "Observably, the primary melanomas revealed more heterogeneous immune cell composition, with comparatively greater variability in CD8+/CD4+ T cells and macrophages." (PMID 40722520, 2025). "B cells promote systemic antitumor immunity by enhancing the effector functions of CD4+ and CD8+ T cells in the spleen and lymph nodes, which leads to the inhibition of melanoma lung metastasis." (PMID 40959278, 2025).
melanoma (continued). "Mechanistically, [212Pb]VMT01 induced immunogenic cell death, sensitizing melanoma cells to ICI therapy and promoting the infiltration of CD3+, CD4+, and CD8+ T lymphocytes within the tumor microenvironment." (PMID 40867277, 2025). "Icariin and icaritin both enhance the anti-cancer response by modulating the function of CD4+ and CD8+ T cells, macrophages, and MDSCs in melanoma, breast, prostate, pancreatic and liver cancers." (PMID 40490812, 2025). "In order to examine this issue, we extracted two signatures consisting of the most potent markers identified in the context of exhaustion and anergy respectively and applied them in the CD4+ and CD8+ T-cell compartment of our melanoma cohort." (PMID 41372921, 2025). "While the overall counts of CD3+, CD4+, and CD8+ T cells remained stable (data not shown), a marked increase in IFNγ expression was detected in circulating CD4+ cells and CD8+ T cells in patients with STS and melanoma 4 weeks after CPMV treatment." (PMID 40386779, 2025). "By performing IHC analysis on melanoma patients‐derived TMA, we observed that male samples are characterised by a higher CD4+ infiltration than female ones." (PMID 39888245, 2025). "CD28-ζ CAR T cells releasing soluble SLAMF6 increased IFN-γ secretion and augmented CD25 upregulation on CD4+ CAR T cells upon CAR engagement by pancreatic carcinoma and melanoma cells." (PMID 40558528, 2025). "A gradual increase in expression of PD1 on CD4+ or CD8+ CD3+ T cells in thicker and more advanced melanomas was noted." (PMID 39825956, 2025). "In melanoma patients after anti-CTLA-4 treatment, peripheral CD4+T-cell clones proliferate and are enriched in corresponding tumors." (PMID 40226614, 2025). "When administered alone or in combination with PD-1 blockade, this vaccine elicited strong tumor-specific CD4+ and CD8+ T cell responses, reinforcing the therapeutic potential of RNA vaccines in melanoma immunotherapy." (PMID 40725830, 2025). "Patients exhibiting concurrent high infiltration of CD4+ Th1 and CD8+ T cells and elevated ICAM, ITGAL, and ITGB2 expression had the best clinical outcomes out of the patients with melanoma." (PMID 40277945, 2025). "In aggressive models of breast cancer and B16-F10 melanoma, this strategy significantly reduced tumor growth and produced antigen-specific CD8+ and CD4+ T-cell responses." (PMID 40872479, 2025). "In the melanoma tumor model, DB2313 enhanced tumor recruitment of CD4+ T helper 1 (Th1) and cytotoxic T/natural killer (NK) cells by targeting TAMs." (PMID 40867314, 2025). "The cellular composition of GCs in cutaneous melanoma metastases resembles that of control tonsillar tissue in that BCL6+CD20+ B cells and BCL6+CD4+ T cells are embedded within a network of CD21+CD23+ FDCs." (PMID 40940789, 2025). "By contrast, conditioned media from IFNγ-treated melanoma cells, which exhibited high levels of kynurenine due to strong IDO1 expression, profoundly inhibited the proliferation of CD4+ as well as CD8+ T cells." (PMID 39962447, 2025). "In a Phase Ib trial, the combination of the NEO-PV-01 neoantigen vaccine with pembrolizumab-enhanced neoantigen-specific CD4+ and CD8+ T cell responses and improved clinical outcomes in advanced melanoma patients." (PMID 39857682, 2025). "Almost all the patient slides in melanoma, HNC, and colorectal cancers show fencing clusters formed by CD8+ or CD4+ T cells and their subtypes." (PMID 41446806, 2025). "In melanoma, dietary supplementation with L‐fucose enhances fucosylation of the MHC‐II molecule HLA‐DRB1 on tumour cells, facilitating CD4+ T cell recruitment and increasing overall immune cell infiltration." (PMID 40673641, 2025). "CD4 TEM cells with a cytotoxic profile (termed CD4 CTLs) expressing granzymes, perforin, and the TF eomesodermin (EOMES) were first identified by flow cytometry in murine melanoma tissue samples and in human solid tumors." (PMID 40571973, 2025).